ENPP1 (ectonucleotide pyrophosphatase/phosphodiesterase 1)
Diseases named in the same sentence as ENPP1 in open-access papers (continued):
Sharing a sentence is not in itself a finding about the gene and the disease.
tumor (continued). "Although the pan-cancer relationship between ENPP1 expression and HRD score was heterogeneous, significant correlations were observed in 11 tumor types." (PMID 41496120, 2026). "A finding reveals that tumour exosomal ENPP1 hinders cGAS‐STING signalling by hydrolysis of 2′3′‐cyclic GMP‐AMP (cGAMP) in immune cells, thereby facilitating tumour immune evasion." (PMID 40032646, 2025). "ENPP1 is widely expressed throughout the body, while ENPP3 is predominantly expressed in immune cells and tumor tissues." (PMID 40535334, 2025). "In vivo, dual ENPP1/ATM inhibition heightened radiosensitivity, compromised tumor cell survival and enhanced STING-TBK1 signaling by preventing ENPP1-mediated cGAMP hydrolysis." (PMID 40506449, 2025). "We confirmed the observed transcriptional upregulation of ITGB4 and the downregulation of ENPP1 and HMGCS1 in BMP4-expressing primary tumours at the protein level." (PMID 39273106, 2024). "Blocking ENPP1 can potentially restore the effectiveness of the STING pathway, thereby enhancing immune-mediated tumor suppression." (PMID 38881902, 2024). "Ecto-nucleotide pyrophosphatase/phosphodiesterase-1 (ENPP1/NPP1), a membrane-bound nucleotide hydrolase hydrolyzes 2’3’-cGAMP and dampen the STING-dependent anti-tumor innate immune response." (PMID 39318624, 2024). "Similar to ENPP1, AGR2 has been reported to have tumour-promoting activity, including the promotion of proliferation, migration, invasion and therapy resistance." (PMID 39273106, 2024). "NK cells and macrophages will target tumor cells bound with the Fc effector active forms for ADCC, and the ENPP1 inhibitor in BiTE format robustly activated T cells." (PMID 37400538, 2024). "The tumor microenvironment (TME) can have high concentrations of extracellular cGAMP, and ENPP1 is frequently upregulated on tumor cells to evade trans cGAMP signaling, potentiating immune evasion and metastasis." (PMID 37400538, 2024). "ENPP1 inhibitor, ZXP-8202 with EC50 value of 20 nM in cell based-assay and ZX-8177 with IC50 of 9.5 nM are reported with 37-60% tumor growth inhibition (TGI) for ZX-8177 in CT26 syngeneic mouse model." (PMID 39318624, 2024). "Other novel BMP4-regulated genes emerged from this analysis, including Ectonucleotide pyrophosphatase/phosphodiesterase 1 (ENPP1), a known suppressor of anti-tumour STING signalling, showing potent downregulation by BMP4." (PMID 39273106, 2024). "The results elucidate the essential function of tumor exosomal ENPP1 in the cGAS‐STING pathway, furthering understanding of the crosstalk between the tumor cells and immune system." (PMID 38498770, 2024). "To understand the pathways activated in the tumor following radiation therapy and VIR3 inhibition of Enpp1, we performed RNASeq of the tumors 4 days following radiation treatment." (PMID 39622844, 2024). "ENPP1 inhibitors (STF‐1623) should, in principle, inhibit both tumor cellular ENPP1 and tumor exosomal ENPP1." (PMID 38498770, 2024). "By hydrolysis of 2’,3’-cyclic GMP-AMP (cGAMP) in the extracellular space, ENPP1 reduces cGAS-STING signaling, further weakening anti-tumor immune response." (PMID 36761762, 2023). "Therefore, we hypothesized that Enpp1 depletion also disfavors primary tumor onset." (PMID 38117852, 2023). "Recent studies have demonstrated that ECM1, ENPP1, TSPAN12 were involved in tumor invasion and metastasis." (PMID 35645555, 2022). "The inhibition of ENPP1 differs from the pharmacologic activation of STING in a few crucial ways, even though they all elicit anti-tumor immunity through the cGAS-STING-TBK1-IRF3 signaling pathway." (PMID 35806118, 2022). "Recently, Li and colleagues demonstrated that the ectonucleotide pyrophosphatase/phosphodiesterase 1 (ENPP1) promotes metastasis by degrading cGAMP and contributing to the production of adenosine (an immune-suppressive and tumor-promoting metabolite)." (PMID 34072037, 2021).
tumor (continued). "Our results showed that the expression of ENPP1 was highly correlated with clinical FIGO staging and tumor cell differentiation." (PMID 33635867, 2021). "Because the MCF7-luc ENPP1-MF cells also expressed GFP, we confirmed that the tumour tissues were derived from MCF7-luc ENPP1-MF cells by detecting GFP expression." (PMID 26065921, 2015). "Taken together, our findings provide novel insights into the ENPP1–HRD axis and suggest that these clusters may serve as a foundation for refining biomarker-driven precision medicine strategies across diverse tumor types." (PMID 41496120, 2026). "This led to the discovery of 36 putative tumor-surface antigens, such as integrin beta-6 (ITGB6), fibroblast growth factor receptor-4 (FGFR4), and ectonucleotide pyrophosphatase/phosphodiesterase 1 (ENPP1)." (PMID 39755633, 2025). "In our system Enpp1 inhibitors do not greatly impact tumor growth alone, but their activity is revealed following radiation therapy." (PMID 39622844, 2024). "The aim of this study is to understand the importance of Enpp1 expression in non-cancer cells of the tumor and how this impacts tumor control by radiation." (PMID 39622844, 2024). "In control, untreated mice tumor growth was not significantly different between wt and Enpp1−/− mice." (PMID 39622844, 2024). "Using both Enpp1 knockout mice and a novel Enpp1 inhibitor, we demonstrate that Enpp1 expression in the non-cancer cells limits tumor control following radiation." (PMID 39622844, 2024). "However, NMRGs with significant AUC values (ENPP1, ENPP2, NAMPT, SIRT1, PARP1, NMNAT1, and PNP) were differentially expressed among tumor grades." (PMID 38254798, 2024). "Importantly, we also show that, as with ENPP1, selectively abolishing ENPP3's cGAMP hydrolysis activity results in diminished cancer growth and metastasis of certain tumor types in a stimulator of interferon genes (STING)-dependent manner." (PMID 38749434, 2024). "Then, we treated ENPP1 knockdown tumor cells (A375, MDA‐MB‐231 and A549 ENPP1‐KD) with HT‐DNA (50 ng mL−1) and subsequently co‐cultured them with THP1‐Lucia ISG cells together with tumor‐derived exosomes treatment." (PMID 38498770, 2024). "Importantly, Enpp1 expression by cancer cells can limit activation of the STING pathway by degrading cGAMP, resulting in decreased tumor control." (PMID 39622844, 2024). "These tumor‐derived exosomes also exhibited dual regulation in the cGAS‐STING pathway by both assisting 2′3′‐cGAMP to enhance STING signaling and hydrolyzing 2′3′‐cGAMP through ENPP1 to inhibit STING signaling." (PMID 38498770, 2024). "Consistent with reports, we observed three different expression patterns of ENPP1 in these tumors, which comprised negative, tumor cell dominant, and stroma dominant." (PMID 38498770, 2024). "Ectonucleotide pyrophosphatase/ phosphodiesterase 1 (ENPP1), which selectively degrades extracellular cGAMP and interferes with immune cell infiltration, is upregulated in TNBC cells with CIN, contributing to resistance to immunotherapy and tumor metastasis." (PMID 37163421, 2023). "Indeed, knockout of ENPP1 in TNBC syngeneic models reduced metastasis to the lung and led to a massive increase in immune cell infiltration at the primary tumor." (PMID 36910138, 2023). "For example, our data highlight the notion that host-derived ENPP1 is not a passive bystander, but rather actively involved in shaping the tumor immune microenvironment." (PMID 38117852, 2023). "Overlap of upregulated genes in the tumor tissue with downregulated genes in the cell line treated with pazopanib identified three genes involved in cancer invasion and metastasis (MMP13, ST6GAL2, and ENPP1)." (PMID 35365682, 2022). "The expression of ENPP1 across PAM50 subtypes (molecular classification) as well as tumor stages did not vary significantly." (PMID 36235254, 2022). "Moreover, the strong expression of ENPP1 is closely related to FIGO staging and differentiation of tumor cells." (PMID 33635867, 2021).
tumor (continued). "MiR-27b expression was low in a subset of the tumour specimens; therefore, ENPP1 expression was determined in these 26 samples and 9 non-tumour controls." (PMID 26065921, 2015). "Molecular functional profiling revealed that these clusters, identified from the pan-cancer samples, exhibited both cancer type nonspecific global characteristics and tumor type-specific features, thereby providing a framework for understanding how ENPP1 and HRD jointly shape tumor biology." (PMID 41496120, 2026). "Indeed, the ability of tumor exosomal ENPP1 to hydrolyze other transporter‐2′3′‐cGAMP is not excluded, and it further enhances the function of tumor‐derived exosomes in innate immune regulation." (PMID 38498770, 2024). "Therefore, therapeutic ENPP1 inhibitors require optimal selectivity for tumor cells and ideally would not be competitive with high levels of ATP and cGAMP in the TME, properties that can be difficult to design using a small-molecule approach." (PMID 37400538, 2024). "In addition, this work demonstrates that radiation is a strong partner for novel Enpp1 inhibitors that may have limited impact as single agents, but strongly enhance CD8-mediated tumor control by radiation therapy." (PMID 39622844, 2024). "Phagocytic macrophages expressing and secreting Enpp1 may limit the availability of both antigen and adjuvant to dendritic cells, which can result in a failure of CD8 T cell tumor control and contribute to the immunosuppressive phenotype of tumor environments." (PMID 39622844, 2024). "This has the potential to be applicable regardless of cancer cell expression of Enpp1, thus Enpp1 expression by the tumor stroma may limit tumor control following radiation across a broad range of patients and tumor types." (PMID 39622844, 2024). "ENPP1 inhibits pro-inflammatory cytokine production, stimulates anti-inflammatory cytokine synthesis, and leverages two GPCR receptors (A2a A2b) to hydrolyze ATP, contributing to increased adenosine signaling in the hypoxic tumor microenvironment of metastatic PCa." (PMID 38435029, 2023). "Furthermore, ectopic over-expression of ENPP1 protein in HLA-A2+ tumor cells did not activate TCR-Ts." (PMID 32395117, 2020). "Importantly, the ENPP1+ tumor cells did not activate TCR1-Ts and TCR2-Ts, and only weakly activated TCR3-Ts." (PMID 32395117, 2020). "We found that while all 3 TCR-Ts could be activated by and kill the MCF7 pulsed with ENPP1436 peptide, they were not activated by and did not kill the ENPP1 overexpressing MCF7 tumor cells." (PMID 32395117, 2020). "However, the strong anti-tumor responses of STING agonists, including cGAMP, may be dampened by the rapid degradation of cGAMP by ectonucleotide pyrophosphatase/phosphodiesterase I (ENPP1)." (PMID 38095464, 2024). "It should be noted that we could not elucidate the molecular mechanism by which ENPP1 induces upregulation of ABCG2 at the mRNA level or the role of ENPP1 in the acquisition of tumour seeding ability; therefore, additional investigations of ENNP1 functions are required." (PMID 26065921, 2015). "Interestingly, the ENPP1-expressing population cDC1 are essential for STING-mediated rejection of established and metastatic murine tumors, and blocking ENPP1 in these cells could enhance the STING pathway and type I interferon response, contributing to anti-tumor immunity." (PMID 39694917, 2024). "Another cell-impermeable, nontoxic specific ENPP1 inhibitor is STF-1623 (Ki,app = 16 nM in an in vitro assay) which delayed tumor growth in Panc02 syngeneic, pancreatic tumor model." (PMID 39318624, 2024). "Of note, MMP13 was specifically expressed within the tumor and not in the normal component; ST6GAL2 and ENPP1 were highly expressed in tumor tissue compared to adjacent normal tissue (log2-foldchange 4.26 and 2.94, respectively)." (PMID 35365682, 2022).
cancer (56 papers, 2015 to 2026). A tumor composed of atypical neoplastic, often pleomorphic cells that invade other tissues. "Rac2 plays an essential role in T cell activation and cytoskeletal remodeling, while ENPP1 is implicated in immune disorders and cancer." (PMID 41257548, 2025). "The association with these diseases make ENPP1 an attractive target for immunotherapy of various cancers and tissue calcification." (PMID 38167594, 2024). "In the context of cancer, ENPP1 overexpression is associated with the development of an immunosuppressive TME." (PMID 38881902, 2024). "High ENPP1 expression in cancer is associated with higher rates of metastasis and resistance to immunotherapy, namely immune checkpoint inhibitors." (PMID 38675916, 2024). "Again, we found that total loss of ENPP1 in cancer cells and host tissue rendered two thirds of the mice metastasis-free." (PMID 38117852, 2023). "After analyzing ENPP1 expression from patients with different cancer stages, it was also observed that ENPP1 expression was associated with cancer progression, with advanced-stage patients having high ENPP1 levels compared to the early-stage patients." (PMID 36235254, 2022). "In clinic, Enpp1 expression has been associated with reduced lymphocytic infiltration in human cancers in accordance with the role of ENPP1 in escaping the immune system." (PMID 35008251, 2021). "Future studies could consider investigating the effects of quercetin and myricetin on ENPP1 when using substrates associated with disease pathogenesis, such as cGAMP, which is linked to cancer." (PMID 38167594, 2024). "Moreover, high activity of ENPP1 has also been linked to crystal deposition diseases such as soft tissue calcification and pseudogout, as well as multiple types of cancer, including lung, breast, and ovarian cancer." (PMID 38167594, 2024). "Interestingly, higher expression of ENPP1 has been directly linked with cancer progression, metastasis, and poor response to immunotherapy." (PMID 39318624, 2024). "In regards to cancer, ENPP1 overexpression causes different cancer phenotypes." (PMID 32887628, 2020). "Using the Enpp1H362A variant that specifically abolishes ENPP1’s cGAMP hydrolysis activity and orthogonal molecular sponges to deplete extracellular cGAMP, we confirmed that cGAMP is the relevant substrate in in vivo cancer models in a manner dependent on downstream STING signaling." (PMID 38117852, 2023). "Inhibition of cGAMP degradation by ENPP1 has emerged as a promising strategy to improve cancer therapies." (PMID 42055331, 2026). "When the cancer type-specific distribution of ENPP1 expression and HRD score were delineated using the k-nearest neighbor approach, each cancer type exhibited a unique territory." (PMID 41496120, 2026). "Conversely, we are approaching a new era of cancer immunotherapy with the ongoing clinical trials of ENPP1 inhibitors." (PMID 40358186, 2025). "In chromosomally unstable metastatic cancer cells, ectonucleotidase ENPP1 reduces immune cell infiltration, and promotes metastasis and resistance to anti-PD-1/PD-L1 treatment via selectively degrading extracellular cGAMP." (PMID 40175357, 2025). "In the last years, ENPP1 has become an attractive target for immunotherapy because of its expression on cancer cells and its capacity to modulate the cGAS/STING pathway." (PMID 39694917, 2024). "In contrast, immune inhibitory genes in cancer cells, e.g., ENPP1, CTNNB1, PRMT5, were depleted after lymphocyte-cancer co-culture." (PMID 38678024, 2024). "In conclusion, targeting ENPP1 offers a dual benefit in cancer therapy by potentially disrupting the immunosuppressive adenosine pathway and by reactivating important immune surveillance mechanisms like the STING pathway." (PMID 38881902, 2024). "Ectodomain phosphatase/phosphodiesterase-1 (ENPP1) is overexpressed on cancer cells and functions as an innate immune checkpoint by hydrolyzing extracellular cyclic guanosine monophosphate adenosine monophosphate (cGAMP)." (PMID 37400538, 2024).
cancer (continued). "ENPP1 has emerged as a promising therapeutic target in cancer immunotherapy and inhibition of ENPP1 augments anticancer immunity via STING-mediated innate immune activation." (PMID 39318624, 2024). "Nevertheless, these data demonstrate that there is variation between murine cell lines and as with human tumors, murine cancer cells can variably express Enpp1." (PMID 39622844, 2024). "The sensing of extracellular cGAMP can be halted by the expression of the enzyme ectonucleotide pyrophosphatase/phosphodiesterase family member 1 (ENPP1) by cancer cells." (PMID 38675916, 2024). "Ectodomain phosphatase/phosphodiesterase-1 (ENPP1) is an extracellular enzyme that promotes immune evasion in the context of cancer progression and metastasis." (PMID 37400538, 2024). "In contrast to the restricted expression of Enpp1, the ability to respond to cGAMP via Sting1 expression was widely shared between cancer cells and infiltrating cell types in this dataset (Fig. 1bii)." (PMID 39622844, 2024). "ENPP1 is overexpressed in many cancers, and ENPP1 inhibitors or anti-ENPP1-drug conjugates for anti-cancer therapy are intensively discussed." (PMID 39694917, 2024). "Indeed, analysis from the TCGA database and early reports reveal that ENPP1 inhibits the infiltration of related immune cells, and high ENPP1 expression is associated with the poor prognosis of many cancers and the reduced overall survival of some cancer patients." (PMID 38498770, 2024). "This information can be used to further elaborate on the function of ENPP1 on these cells, as well as to evaluate and prevent potential systemic effects of ENPP1 inhibition, currently discussed as anti-cancer therapy." (PMID 39694917, 2024). "To test the impact of Enpp1 expressed by non-cancer cells on the response to radiation therapy we analyzed Enpp1−/− mice." (PMID 39622844, 2024). "Ectonucleotide pyrophosphatase phosphodiesterase I (ENPP1), an extracellular enzyme, was the only metazoan hydrolase known to regulate cGAMP levels to dampen anti-cancer immunity." (PMID 38749434, 2024). "A few ENPP1 small molecule inhibitors have advanced to early clinical stages for potential use as cancer immunotherapeutics that enhance the STING-mediated immune response." (PMID 39318624, 2024). "While the function of ENPP1 in the context of cancer is currently under intensive investigation, the cell surface expression on human immune cells is barely known." (PMID 39694917, 2024). "Another preclinical candidate AVA-NP-695, from Avammune Therapeutics is a selective and highly potent ENPP1 inhibitor, which apart from its immunomodulatory effect also modulates cancer metastasis." (PMID 39318624, 2024). "ENPP1 impacts cancer immunity primarily by shifting the ATP-adenosine balance towards adenosine, an immunosuppressive agent that inhibits effector T cells and promotes regulatory T cell activities." (PMID 38881902, 2024). "By degrading cGAMP, a secondary messenger in the STING pathway, ENPP1 dampens the immune response to cancer cells." (PMID 38881902, 2024). "While ENPP1 has been a highly sought-after target in cancer therapeutics, developing drug-like ENPP1 inhibitors has been challenging." (PMID 38095464, 2024). "In summary, our scRNA-seq data suggest that cancer-cell-derived ENPP1 catalytic activity attenuated T cell activation while promoting exhaustion in primary tumors and sites of metastasis." (PMID 38117852, 2023). "We next examined how overexpression of WT ENPP1 in cancer cells affected STING activation in cGAMP responder cells as measured by their combined Ifitm1, Ifitm2, and Ifitm3 expression (Ifitms)." (PMID 38117852, 2023). "Cancer- and host-derived ENPP1 contribute equally to intratumoral cGAMP degradation activity, while tissue-derived ENPP1 is mainly responsible for cGAMP degradation in serum." (PMID 38117852, 2023).